CCL18 (C-C motif chemokine ligand 18)
Diseases named in the same sentence as CCL18 in open-access papers (continued):
Sharing a sentence is not in itself a finding about the gene and the disease.
tumor (continued). "Moreover, TAMs, as the most cellular component in tumor stroma, were reported to induce CAF differentiation and augment tumor growth via CCL18 secretion." (PMID 33122682, 2020). "It has been shown that, in the presence of YKL-39+CCL18- TAM or YKL-39-CCL18+ TAM in a tumor, patients did not respond to neoadjuvant chemotherapy." (PMID 33114763, 2020). "Notably, we identified a subset of M2 macrophage with high expression of CCL18 and transcription factor CREM that was enriched in advanced HCC patients, and potentially participated in tumor progression." (PMID 33298893, 2020). "In mouse models of breast cancer, macrophages contribute to tumor progression through a variety of mechanisms including IL-10 and arginase 1 (Arg1)-mediated immunosuppression, MMP 7/9 and CCL18-induced matrix remodeling, and EGF and TNFα-stimulated tumor cell migration and metastasis." (PMID 28881599, 2017). "For instance, tumor and T-regulatory cell-derived IL-10 can skew macrophages toward an anti-inflammatory phenotype characterized by activation of STAT3 and increased expression of CD163, CCL18, and SOCS3." (PMID 28881599, 2017). "Besides the pro-angiogenic and immunosuppressive effects, TAMs can also facilitate tumor cell invasion and metastasis via secreting various proteolytic enzymes, cytokines and chemokines such as MMPs, cathepsins, EGF, and CCL18." (PMID 28848446, 2017). "Two genes were over-expressed in the aggressive human specimens compared with the non-aggressive tumor, CCL18 (p = 0.03) and HTRA3 (p = 0.04)." (PMID 29100308, 2017). "Furthermore, subcutaneous homografts models showed the increased tumor growth and tumor vascularization with the CCL18 stimulation, and the expression of Ki67, PCNA, and CD31 in CCL18 stimulation mice was also significantly increased." (PMID 25197632, 2014). "Notably, serum CCL18 levels are significantly elevated in non-small cell lung cancer (NSCLC) patients and exhibit a negative correlation with both prognosis and overall survival, suggesting its key role as a tumor-promoting chemokine." (PMID 41445742, 2025). "Taken together with previous findings on their differential expression in BRCA and other malignancies, these data support the notion that CCL18 and EGF not only serve as markers of tumor biology but may also actively influence immune cell dynamics and tumor–immune interactions." (PMID 40692603, 2025). "Moreover, in vivo, examinations validated the speculation that LC enhances tumor progression and metastasis in RCC mice via the secretion of excessive chemokine (C-C motif) ligand 18 (CCL18) and TGF-β1." (PMID 38962453, 2024). "Additionally, in metastatic tumors, MRC1 + CCL18 + macrophages, SPP1 + macrophages, and neutrophils were found to have significantly enhanced expression, suggesting a correlation between macrophage phenotype and tumor stage." (PMID 39068459, 2024). "However, CCL18 administration to xenografts formed by MCF-7 cells alone did not influence the effects of chemotherapy or tumor growth in vivo." (PMID 36418470, 2023). "CCL18, a chemokine mainly secreted by macrophages and dendritic cells, has been shown to play important roles in the reprogramming of TME by the recruitment of immune cells and direct regulation of multiple functions of tumor cells, such as cell proliferation, EMT, and metastasis." (PMID 36217054, 2023). "Moreover, CCL18 released from neuroprotective microglia, can block the recruitment of T cells in tumors, reduce the suppressive effect of Treg cells, and regulate the immune response by inhibiting the CCL18-PITPNM3 signaling pathway in tumor-related research." (PMID 36774485, 2023). "In addition, targeting CCL18 by anti-CCL18 antibody could inhibit the formation of CD10+GPR77+ CAFs and recover the chemosensitivity in vivo, leading to effective tumor control." (PMID 36418470, 2023).
tumor (continued). "UCs are capable of secreting a variety of cytokines in the tumor microenvironment, we only explored the role of CCL18 and did not investigate whether other cytokines also contribute to UCs." (PMID 35059433, 2021). "The proliferation and metastasis of tumor cells can be promoted by M2 macrophages by releasing anti-inflammatory factors such as IL-10 and TGF-β, immunosuppressive factors such as PGE2, arginase-I, somatomedins such as EGF, CCL18, and HIF-1α and pro-metastasis factors such as MMPs, uPA, and uPAR." (PMID 34506209, 2021). "CCL5 and CCL18 up-regulate the activity of various glycolysis factors, including lactate dehydrogenase A (LDHA) and glucose-6-phosphate dehydrogenase (G6PD), which can advance glycolysis in tumor cells, lead to accumulation of lactic acid in TME and restrain the immune system’s anti-tumor reaction." (PMID 34368156, 2021). "However, CCL18 is not a chemotactic agent for monocytes or macrophages, which is why it does not affect the recruitment of TAMs into the tumor niche." (PMID 33114763, 2020). "In addition, TAM-derived prostaglandin E2 (PGE2), IL-10, and indoleamine 2,3-dioxygenase play important roles in the induction of Tregs and TAM-derived CCL17, CCL18, and CCL22 are chemotactic factors for Tregs, which results in the suppression of T cells in the tumor microenvironment." (PMID 28241846, 2017). "In this study we showed that inhibiting naive CD4+ T cell recruitment by knocking down PITPNM3 in tumor-bearing humanized mice could reduce TI Tregs, restore immune killing of tumors and suppress tumor growth and metastases, confirming the role of PITNM3 recognition of CCL18 in TI Treg biogenesis." (PMID 28290464, 2017). "However, CCL18 treatment did not result in miR98 reduction in the tumor xenografts infected with lenti-miR98." (PMID 26244871, 2015). "In addition to the increased levels of a macrophage marker in large tumors, our study suggests an association between the mRNA levels of the cytokines CCL5, CCL18, and GDF15, as well as the transcription factor IRF4, and VS tumor volume, which has not yet been investigated in VSs." (PMID 39272860, 2024). "In addition, TAMs modulate tumor metastasis by regulating the EMT process through STAT/miR-506-3p/FoxQ1 signaling and TAT/miR-506-3p/FoxQ1 pathway and promote extracellular matrix degradation via secreting matrix metalloproteinases and C-C motif chemokine ligand 18 (CCL18)." (PMID 36845095, 2023). "However, there are no detailed studies on the effects of CCL18 on CAFs in the neoplastic tumor." (PMID 33114763, 2020). "Furthermore, we could not demonstrate that elevated or rising CCL18 serum concentrations correspond to tumor activity in terms of progression or worse survival, although the aim of this study was prognostic role of CCL18 concerning RILT." (PMID 28957436, 2017). "In our study we could not observe any effect of the different CCL18 concentrations also after adjusting for progression within the first 6 months after treatment completion, suggesting that these results did not interfere with the tumor activity." (PMID 28957436, 2017). "Thus, although there might be an influence of age on the CCL18 serum level, the observed differences between controls and tumor patients can not be explained by the different median ages of these groups." (PMID 22848587, 2012). "CCL18 was found in both the cytoplasm and cell membrane of OSCC cells and was predominantly produced by cancer epithelial cells, as opposed to tumor-infiltrating macrophages." (PMID 26919103, 2016). "Interestingly, we found that blocking CCL18, but not IL-6 and IL-8, significantly inhibited the upregulation of CD10 and GPR77 in NBFs exposed to chemoresistant tumor CM." (PMID 36418470, 2023).
tumor (continued). "Differential gene expression showed an enrichment of genes involved in T cell recruitment (CXCL9, CXLC10) and interferon-gamma activity (GBP1, STAT1) in the macrophage compartment of responding tumours, while non-responders were enriched in immunosuppressive markers (GPNMB, CCL18)." (PMID 38030622, 2023). "Interestingly, CCL18-activated NBFs, but not TGF-β-treated NBFs, enhanced the survival of cocultured tumor cells exposed to the chemotherapeutic docetaxel or cisplatin." (PMID 36418470, 2023). "CCL18 also increases the expression of cancer stem cell markers, is involved in angiogenesis by acting on vascular endothelial cells via PITPNM3, and affects non-cancer cells in the tumor niche." (PMID 33076281, 2020). "While CCL18 has recently been discovered to bind and signal through CCR8, it also signals through a variety of non-traditional receptors, with the most critical in neoplastic disease being phosphatidylinositol transfer protein 3 (PITPNM3)/PYK2 N-terminal domain-interacting receptor 1 (Nir1)." (PMID 38339310, 2024).
cancer (177 papers, 2010 to 2025). A tumor composed of atypical neoplastic, often pleomorphic cells that invade other tissues. "The progression of cancer necessitates evasion of immune surveillance, and CCL18, which is secreted by M2 macrophages, serves as a hallmark of macrophage activation." (PMID 38511143, 2024). "CCL18 has been implicated in the stimulation of angiogenesis as well as cancer cell migration, invasion, and epithelial-to-mesenchymal transition." (PMID 37024866, 2023). "For the quantification of PD-L1 expression (biomarker in cancer immunotherapy), CCL18, TNFAIP6, and BCL2A1 had higher diagnostic efficiency (AUC > 0.7)." (PMID 35265629, 2021). "This founding underlines the importance of less-invasive assay of serum CCL18 in clinical management setting, which is more superior to other cancer biomarkers assayed via immunohistochemistry or qPCR in cancer tissue biopsy or surgery." (PMID 31839826, 2019). "GM-CSF derived from cancer cells induced neighboring macrophages to produce CCL18, which in turn caused mesenchymal-like changes of cancer cells through the activation of NF-κβ." (PMID 28220123, 2017). "Recently, Chen and colleagues linked TAM-produced CCL18 with cancer cell invasiveness and identified PITPNM3 (a membrane-associated phosphatidylinositol transfer protein) as its receptor." (PMID 25165728, 2014). "This leads to the question if CCL18 is directly involved in pathogenic processes in cancer diseases." (PMID 23349697, 2013). "Importantly, upregulation of CCR2 and its ligand CCL2 has also been found in PCa and associated with cancer advancement, metastasis, and relapse, and upregulation of CCL18 has been shown to correlate with malignant progression of PCa." (PMID 36321189, 2023). "The effect of immunosuppressive effects on tumors may be larger than the causal association between CCL18 and cancer." (PMID 38075694, 2023). "C‐C motif chemokine ligand 18 (CCL18), a member of the CC chemokine family, was reportedly expressed in monocytes, macrophages, and immature dendritic cells and associated with the progression of malignant tumors." (PMID 30216450, 2019). "Firstly, our current study only focus on cytokine CCL18, it is reasonable to assume that other secretory proteins may also tightly associated with M2 TAMs mediated cancer progression." (PMID 30181713, 2018). "CCL18 is associated with some human cancer types including ovarian cancer." (PMID 29170526, 2017). "CCL18 is a macrophage cytokine implicated in promoting cancer metastasis." (PMID 29100308, 2017). "Indeed, CCL18 is associated with immunosuppressive functions and cancer immune evasion." (PMID 38347955, 2023). "However, there was an inverse association between CCL15 and CCL18 and cancers in our analysis." (PMID 38075694, 2023). "Breast TAMs secrete CCL18, which downregulates miR-98 and miR-27b, enhancing angiogenesis, adhesion, and migration of cancer cells." (PMID 40692603, 2025). "In ovarian cancer, lactate is elevated in the serum of cancer patients and supports tumor growth via the activation of CCL18 expression via H3K18 lactylation in macrophages to promote tumorigenesis." (PMID 39516356, 2024). "Annexin A2 (AnxA2)-a member of the calcium dependent phospholipid binding proteins was proposed as a downstream molecule of the CCL18-PITPNM3 signaling in cancer cells." (PMID 39044824, 2024). "In malignant tumors, the polarized M2 macrophages produce and secrete cytokines such as CCL18, CCL20, CCL22, IL10, TGFB1, and GDF15." (PMID 39272860, 2024). "CCL18 induces macrophage maturation into an M2‐like phenotype itself and is known to be produced by TAMs in several different types of cancers." (PMID 38037545, 2023). "In fibroblasts, CCL18 activates NF-κB pathway and produced a tremendous amount of IL-6 and IL-8, which induce the stemness and chemoresistance of cancer cells." (PMID 36418470, 2023).
cancer (continued). "Compared with other 33 cancer types in The Cancer Genome Atlas (TCGA), CCL18 was co-expressed with multiple immune checkpoints in 14 cancers." (PMID 36850011, 2023). "This demonstrated the great potential of CCL18 to be served as a pan-cancer target for future immunotherapy." (PMID 36850011, 2023). "The NF-κB signaling pathway has been confirmed to be essential for the epithelial–mesenchymal transition (EMT) of cancer cells induced by CCL18-producing TAMs." (PMID 36418470, 2023). "PITPNM3 and CCL18 are reported to participate in cancer cell activation, migration, and the progress of immune tolerance." (PMID 35609322, 2022). "The protein level of CCL18 was determined by immunohistochemistry (IHC) and the expression of CCL18 in TCGA pan‐cancer was extracted." (PMID 36285700, 2022). "The positive feedback loop formed by Granulocyte–macrophage colony-stimulating factor (GM-CSF)-CCL18 facilitates cancer cells to maintain or promote their mesenchymal phenotype, creating a positive condition for cancer cell metastasis." (PMID 36510315, 2022). "Knockdown of PITPNM3 by siRNAs will significantly abrogate CCL18 conducted cell metastasis in these 13 cancer cell lines." (PMID 36285700, 2022). "Similar to most types of cancers, we confirmed that CCL18 stimulation increased the ICC cells proliferation and metastasis." (PMID 35609322, 2022). "Ascitic TAMs from OC patients express high levels of CCL18, the immunosuppressive factor involved in cancer immune evasion." (PMID 35682890, 2022). "CCL18, one of the major cytokines released by TAMs, enhances cancer cell metastasis by activating the NF-kB signaling pathway in breast cancer metastasis." (PMID 36510315, 2022). "This phenomenon is due both to the lactate-dependent abrogation of the secretion of proinflammatory cytokines (IL-12, TNFα, IL6, and IL1β) and to the induction of CCL18 secretion, which, in turn, stimulates cancer cell EMT." (PMID 35054987, 2022). "C-C motif chemokine ligand 18 (CCL18) is an example of the intersection between immune cells and cancer cells." (PMID 36499622, 2022). "This concept was further confirmed with human breast tumors, revealing that high GM-CSF expression significantly corresponds to CCL18-expressing macrophages, cancer cell EMT and metastasis, and poor clinical outcome." (PMID 33968034, 2021). "Two other molecules have been found to be functional receptors of CCL18, but only in cancer: PITPNM3 and G protein-coupled receptor 30 (GPR30)." (PMID 33918621, 2021). "CCL18 released by TAMs in MDA-MB-231 breast cancer tumors promotes the invasiveness of cancer cells by inducing integrin clustering, enhancing their adherence to the extracellular matrix, which is mediated by the CCL18 receptor PITPNM3." (PMID 34638388, 2021). "Emerging evidence indicates that CCL18 serves numerous functions not only closely related to immune and inflammatory modulation, but also involved in cancer progression." (PMID 33795528, 2021). "In a humanized murine model, anti-GM-CSF and anti-CCL18 both reversed the epithelial–mesenchymal transition (EMT) state of cancer cells, inhibiting metastasis." (PMID 33968034, 2021). "Our data showed that CCL18 was the main chemokine increased in OSCC, associated to cancer cells mainly by immunohistochemical analysis." (PMID 34025655, 2021). "Specifically, research is needed on the simultaneous application of multiple therapeutic approaches, such as blocking the activity of CCL18 and other pro-cancer factors." (PMID 33114763, 2020). "Chemokine (C–C motif) ligand 18 (CCL18), a member of the CC subgroup of chemokines, is involved in the tumor microenvironment and plays a critical role in several cancers including OSCC4–7." (PMID 32948745, 2020). "Nevertheless, more research is required to link CCL18 expression with the response to anti-cancer theraphy." (PMID 33114763, 2020).